DICER1 (dicer 1, ribonuclease III)
Diseases named in the same sentence as DICER1 in open-access papers (continued):
Sharing a sentence is not in itself a finding about the gene and the disease.
lung cancer (30 papers, 2007 to 2026). A malignant neoplasm involving the lung. "Previous in vivo studies in retinoblastoma, prostate, or lung cancer have reported that the loss of a single allele of Dicer1 enhances tumorigenesis, while loss of both inhibits this process." (PMID 39409030, 2024). "Downregulation or lower expression of DICER1 is significantly associated with lung cancer survival, breast and endometrial cancer progression and recurrence, or stemness and metastatic characters of colon cancer." (PMID 25742789, 2015). "The missense mutation c.A3334G (p.N1112D) of DICER1 was identified in both the lung cancer patients, namely, the affected mother (I:1) and the second daughter (II:2); however, it was absent in the other members of the family." (PMID 26241669, 2015). "None of the investigated polymorphisms in POLR2A, RNASEN and DICER1 showed significant association with lung cancer risk or lung cancer survival either overall or by subgroups of histology or smoking status." (PMID 21102586, 2010). "However, next-generation sequencing revealed no glioblastoma-associated genetic alterations but did reveal a mutation in DICER1, a gene encoding an RNA endoribonuclease implicated in malignant lung tumors." (PMID 42211592, 2026). "In addition, a recent study showed that downregulating DICER1 expression that is also associated with regulation of miRNA transcripts promotes tumorigenesis in vitro and in a mouse lung cancer model." (PMID 31214494, 2019). "However, in contrast to DROSHA, increased expression of DICER1 was associated with longer survival in various cancers including lung cancer." (PMID 26156018, 2015). "Additionally, for our analysis we selected the genomic regions of miR-155 and miR-17 (identified in one meta-analysis), which were consistently associated with poor prognosis of lung cancer, as well as two genes (DICER1 and DROSHA) encoding miRNA processing enzymes." (PMID 26156018, 2015). "For instance, in lung cancer research, it has been demonstrated that Dicer1 functions as a haploinsufficient tumor suppressor, with partial loss of Dicer1 promoting tumor development." (PMID 40666073, 2025). "Altered DICER1 expression has been documented in various tumors, such as breast, ovarian, colorectal, and lung cancers." (PMID 35876890, 2022). "Here, we showed that APE1 up-regulation in lung cancer positively correlates with an increased expression of miRNAs that target DICER1, thus affecting EMT-driven metastatic pathways." (PMID 35876890, 2022). "In particular, low levels of DICER1 in lung cancer are known to correlate with a poor clinical outcome; whereas high DICER1 expression levels entailed a significantly better prognosis." (PMID 35876890, 2022). "Our findings, suggesting that APE1 modulates DICER1 expression via miR-33a and miR-130b, reveal new mechanistic insights on DICER1 regulation, which are of relevance in lung cancer chemoresistance and cancer invasiveness." (PMID 35876890, 2022). "Following successful transfection, RT-qPCR and Western blot assay were utilized for evaluating the involvement of miR-let-7a in regulation of DICER1 expression in lung cancer cell line." (PMID 30383637, 2018). "In this study we analyzed the somatic copy number variation of 14 miRNA genes frequently found to be either over- or underexpressed in lung cancer, as well as two miRNA biogenesis genes, DICER1 and DROSHA, in non-small-cell lung cancer (NSCLC)." (PMID 26156018, 2015). "Deletion of Dicer abrogates the production of mature miRNAs, and conditional deletion of Dicer1 enhances lung tumour development in a K-Ras-induced lung cancer mouse model." (PMID 20859290, 2010). "We analysed 12 SNPs in POLR2A, RNASEN and DICER1 genes in 1984 cases and 2073 controls from the Environment And Genetics in Lung cancer Etiology (EAGLE) study." (PMID 21102586, 2010). "Further functional studies can clarify the mechanism of DICER1 in lung cancer." (PMID 26241669, 2015).
lung cancer (continued). "Interestingly, a recent study showed that downregulating DICER1 expression promotes tumorgenesis in vitro and in a mouse lung cancer model." (PMID 17922911, 2007). "Furthermore, miR-let-7a regulates DICER1 and may be a critical predictive marker of lung cancer brain metastasis." (PMID 35885514, 2022). "In the pathogenesis of lung cancer, Kirsten rat sarcoma viral oncogene homologue (KRAS) mutation-driven lung cancer causes increased aggressiveness and tumor size by gene ablation of the miRNA processing enzyme DICER1, suggesting that miRNA functions are important for suppressing cancer." (PMID 34072894, 2021). "While global down-regulation of miRNAs in many tumors have been reported, it was also reported that heterozygosity for the Dicer1 allele, but not complete loss of Dicer1 alleles, enhances tumor development in K-ras-driven lung cancer and RB-driven retinoblastoma models." (PMID 24023722, 2013). "There is a dose-dependent correlation between the copy number categories and the expression of DICER1 and DROSHA in lung cancer (based on TCGA Cancer Genome ATLAS data)." (PMID 26156018, 2015). "Some studies have shown that the expression of hsa-mir-139-5p in human lung cancer cell lines inhibits the activity of DICER1, but does not inhibit PPP2R2A or LATS2." (PMID 35794555, 2022).
colorectal cancer (27 papers, 2013 to 2023). A primary or metastatic malignant neoplasm that affects the colon or rectum. "In conclusion, colorectal cancer risk was related to an interactive effect between dietary lutein/zeaxanthin intake and the DICER1 rs3742330 polymorphism." (PMID 30833603, 2019). "There is one report of an association of colorectal cancer risk with 3′‐UTR polymorphisms in DICER1 and other miRNA genes." (PMID 30672147, 2019). "It is unclear whether dietary lutein/zeaxanthin intake in colorectal cancer is associated with microRNA processing involved in DICER1 cleavage for messenger RNA translation." (PMID 30833603, 2019). "We investigated whether dietary lutein/zeaxanthin intake affects colorectal cancer risk in patients with a DICER1 rs3742330 polymorphism." (PMID 30833603, 2019). "Paradoxically, the same tRNAArg derivatives produced in a DICER1-dependent mechanism can also drive progression of colorectal cancer under hypoxic conditions." (PMID 35625858, 2022). "In this hospital-based case-control study, we recruited 923 colorectal cancer patients and 1,846 controls based on eligibility criteria, a semiquantitative food frequency questionnaire and the DICER1 rs3742330 genotype." (PMID 30833603, 2019). "The impairment of the miRNA biogenesis gene DICER1 in colorectal cancer cells promotes tumor initiation and metastasis by endowing colorectal cancer cells with stem cell properties and EMT phenotypes." (PMID 26146543, 2015). "Of note, the overexpression of DICER1 has been suggested to predict poor survival in colorectal cancer." (PMID 23135352, 2013). "Examination of two colorectal cancer cell lines representing primary carcinoma or metastatic stages of the disease revealed decreased DICER1 and increased Alu RNA with cancer progression, consistent with Alu RNA being degraded by DICER1." (PMID 32611613, 2020). "Our analysis suggests that germline DICER1 P/LP variation does not contribute significantly to the risk of development of colorectal cancers." (PMID 30672147, 2019). "Additionally, previous reports have demonstrated that miR-130b regulated EMT through targeting PPARG in HCC, colorectal cancer and glioma and through targeting DICER1 in endometrial cancer." (PMID 28107197, 2017). "Whereas low DICER1 expression has been correlated with worse prognosis in chronic lymphocytic leukemia and melanoma, high expression has been correlated with reduced survival in prostate adenocarcinomas and colorectal carcinomas." (PMID 26444668, 2015). "There were no significantly discordant genes between primary colorectal cancer and CRLM; however, CDK12, ERBB3 and DICER1 were exclusively mutated in CRLM." (PMID 37057593, 2023). "We observed no germline P/LP DICER1 variation in the 410 TCGA participants with colon adenocarcinoma or in the 1,006 individuals with familial early‐onset colorectal cancer from the CanVar study." (PMID 30672147, 2019).
thyroid tumor (27 papers, 2016 to 2025). A benign or malignant neoplasm affecting the thyroid gland. "Germline and somatic DICER1 mutations have been implicated in various thyroid tumours, further supporting the link between miRNA pathway components and thyroid disease." (PMID 41104964, 2025). "More recently, high-grade thyroid tumors in children and young adults have been associated with germline and somatic DICER1 variants." (PMID 40448797, 2025). "When stratified by age, pediatric FTC cases displayed a markedly higher prevalence of DICER1 mutations (44.4% vs. 4.6% in adults), supporting previous findings that emphasize the distinct molecular drivers in pediatric thyroid tumors." (PMID 41590496, 2025). "Germline mutations in DICER1 increase susceptibility to conditions including thyroid neoplasms, as part of DICER1 syndrome, also known as autosomal dominant hereditary pleiotropic tumour syndrome." (PMID 41104964, 2025). "Germline mutations in Dicer1 cause Dicer1 syndrome, a hereditary disorder that predisposes individuals to a variety of tumors, including thyroid neoplasms." (PMID 41002430, 2025). "A more recent bi-institutional study identified atrophic changes associated with DICER1 mutations in follicular-patterned thyroid tumours." (PMID 41104964, 2025). "Our data, when considered alongside previous observations, suggest that the majority of DICER1 mutations in thyroid tumors are indeed somatic, even in cases of biallelic mutations." (PMID 38252873, 2024). "It is not known if atrophic changes are unique to follicular cell-derived thyroid tumors or if they are also visualized in unrelated thyroid tumors with DICER1 mutations, for example, thyroblastoma." (PMID 38637342, 2024). "In particular, specific features such as macrofollicular growth and atrophic changes appear to be strongly coupled to DICER1 mutations in follicular-pattern thyroid tumors." (PMID 38637342, 2024). "Somatic and biallelic DICER1 mutations are reported in subsets of thyroid tumors, supporting the role of this gene in thyroid tumor development." (PMID 38637342, 2024). "It is important to note that biallelic DICER1 somatic inactivation(through two separate mutations occurring in trans) is a commonpattern across all DICER1-related thyroid neoplasms and does notautomatically indicate germline involvement." (PMID 39601261, 2024). "In the thyroid tumors studied, atrophic changes were noted in 20 out of 26 DICER1-mutated cases (77%), compared to 2 out of 35 DICER1 wild-type cases (5%)." (PMID 38637342, 2024). "Initially, DICER1 kindred with differentiated thyroid carcinoma were shown to carryadditional somatic hotspot DICER1 mutations, suggesting a biallelicinactivation pattern for thyroid tumors arising in a syndromic setting." (PMID 39601261, 2024). "Pediatric thyroid tumors are a particularly interesting model to dissect the effects of DICER1 mutations on miRNA and mRNA changes." (PMID 36896180, 2023). "Although patients with DICER1 hotspot mutations have well differentiated thyroid tumors of follicular cell origin and are at low risk for lymph node metastasis, a fraction of cases are associated with high-risk PTC or PDTC." (PMID 36896180, 2023). "DICER1 RNase IIIb mutations are found in both benign and malignant follicular derived thyroid tumors, predominantly in follicular-patterned lesions." (PMID 36896180, 2023). "Given the indolent nature of the great majority of DICER1-associated thyroid tumors, the SIOPE HGWG and CanGene-CanVar advise annual neck palpation from age 8 to age 20 years." (PMID 34170462, 2021). "Gain- and loss-of-function assays revealed that DICER1 regulates NKX2-1 expression in thyroid tumor cells and vice versa, thus establishing a positive feedback loop between both proteins." (PMID 33176626, 2021). "The great majority of DICER1-associated thyroid tumors reported to date behaved in an indolent manner." (PMID 34170462, 2021).
thyroid tumor (continued). "In our cohort of thyroid tumours, mutations in commonly affected regions of the DICER1 gene seem to be a rare event." (PMID 32163919, 2020). "At the other end of the spectrum, DICER1-associated thyroid tumors have been reported in pediatric/young adults showing histopathological features consistent with PDTC, including STI growth pattern, increased mitotic activity, necrosis, extensive vascular invasion, and lymph node/distant metastases." (PMID 40448797, 2025). "This proposed algorithm to predict DICER1 mutations in follicular-patterned thyroid tumours could identify individuals with syndromic forms of the disease, preventing the consequences of a late diagnosis of malignancy." (PMID 41104964, 2025). "DICER1 mutations also characterize thyroblastoma, a very rare embryonal thyroid tumor." (PMID 41175860, 2025). "In this study, we analyzed the characteristics of seven DICER1-associated thyroid tumors detected in four pediatric patients, three of them with germline pathogenic variants; the tumors were well-circumscribed or encapsulated, but capsular and/or vascular invasion was detected in five." (PMID 40448797, 2025). "This is a limitation since a more in-depth molecular study of morulae could lead to a better understanding of phenotypic/genetic relationships, particularly in the context of WNT/β-catenin-induced differentiation in DICER1-associated thyroid tumors." (PMID 40892116, 2025). "DICER1 mutations identified in thyroid neoplasms were grouped under several distinct diagnoses." (PMID 41104964, 2025). "This tumor broadens the spectrum of DICER1-associated thyroid tumors." (PMID 40892116, 2025). "Individuals with germline DICER1 mutations have a 16-fold increased risk of thyroid tumours." (PMID 41104964, 2025). "Finally, somatic DICER1 mutations are usuallyreported in thyroblastoma, an embryonal high-grade triphasic thyroid neoplasm thatis usually clinically aggressive." (PMID 39601261, 2024). "To summarize, based on morphological and histological characteristics, we suggest an algorithm that could be used to predict DICER1 mutations in follicular-patterned thyroid tumors a priori." (PMID 38637342, 2024). "Subsequent studies aiming tocharacterize DICER1 gene status in sporadic tumors have describedrecurrent somatic DICER1 alterations, thereby adding evidence for acontributory role for this mutational inactivation also in sporadic thyroid tumors,including FTAs, FTCs and PTCs." (PMID 39601261, 2024). "Mutations of DICER1 in thyroid tumors are quite rare (3.6% from COSMIC)." (PMID 37867524, 2023). "Therefore, genome-wide miRNA/mRNA expression studies will be fundamental to determine tissue-specific miRNA signatures associated with DICER1-driven thyroid tumors and identify oncogenic pathways activated by RNase IIIb hotspot mutations." (PMID 36896180, 2023). "Indeed, DICER1 hotspot mutations have been reported in human thyroid neoplasms of follicular cell origin, including adenomas, papillary thyroid carcinoma (PTC), follicular thyroid carcinoma (FTC), and poorly differentiated thyroid cancers (PDTC)." (PMID 36896180, 2023). "Moreover, as the detection rate of DICER1 mutations in thyroid tumors will rise as more pathology centers rely on next-generation sequencing, identifying potential genotype–phenotype correlations is crucial, especially for centers that require specific conditions for case submission for sequencing." (PMID 38637342, 2024). "A subsequent immunohistochemical study on various DICER1-driven lesions highlighted how PRAME was generally poorly expressed or negative in multinodular goiter nodules or in well-differentiated thyroid tumors." (PMID 40448797, 2025). "At this time point, the amount of TUNEL-positive cells was significantly increased in RET/PTC3 Dicer1(−/−) thyroid tumors." (PMID 41002430, 2025). "In contrast, thyroid tumors from RET/PTC3 Dicer1(+/+) mice showed higher growth and continued to increase in size over time as expected." (PMID 41002430, 2025).